RN7SL838P (RNA, 7SL, cytoplasmic 838, pseudogene)
Gene: Miscellaneous RNA gene on chromosome 11 (440,399 to 440,693, reverse strand). Ensembl gene ENSG00000243562.
Homologues: Orthologues: chimpanzee Metazoa_SRP (90% identical), macaque Metazoa_SRP (80% identical), rabbit Metazoa_SRP (63% identical). Paralogues in human: RN7SL1 (76% identical), RN7SL3 (76% identical), RN7SL2 (75% identical), RN7SL5P (72% identical), RN7SL126P (72% identical), RN7SL14P (72% identical), RN7SL493P (72% identical), RN7SL543P (72% identical), RN7SL566P (72% identical), RN7SL480P (71% identical), RN7SL709P (71% identical), RN7SL220P (71% identical), and 698 more.